ALB (albumin)
Diseases named in the same sentence as ALB in open-access papers (continued):
Sharing a sentence is not in itself a finding about the gene and the disease.
tumor (continued). "To determine whether the albumin concentration improves the prognosis of HCC in patients, we aimed to determine the effect of Alb concentration on overall survival (OS), tumor invasion and metastasis in patients with the same liver function (ALBI grade) at the time of primary HCC diagnosis." (PMID 41008815, 2025). "Thus, cytosolic NCOA3 may promote tumor progression by downregulating PTEN activity for PIP3-mediated macropinocytosis and thereby ALB uptake and energetics during cell migration." (PMID 40186033, 2025). "In tumor patients, AFR comprehensively reflects nutritional status, inflammatory response and coagulation function—distinguishing it from single biomarkers like ALB and NLR, where ALB only mirrors nutritional or hepatic synthetic function and NLR solely captures inflammatory status." (PMID 41256327, 2025). "Among the five genes, analyses of the TCGA + GTXe44 datasets and GSE14520 patients with HCC showed that NCOA3 could be functionally related to TM4SF5 and positively higher in tumor tissues, unlike ALB levels." (PMID 40186033, 2025). "First, methodologies for the detection of serum tumor markers (AFP, AFP-L3% and PIVKA-II) and laboratory tests (TBIL, ALB and PLT) vary by clinical settings, so the observed efficacy of serum tumor markers and diagnostic models may be different from those in this study." (PMID 40708828, 2025). "Interestingly, hepatic expression and production of negative APPs, including albumin, were shown to be reduced in tumor-bearing or infected rodents." (PMID 40124481, 2025). "It is, thus, noteworthy that the same albumin binder may not be the most favorable for each tumor-targeting agent." (PMID 38610940, 2024). "Albumin, an acute phase reactant, is among one of several factors in pre‐operative PDAC patients that is associated with early recurrence and shorter survival regardless of tumour location." (PMID 38123146, 2024). "Albumin coating of a range of synthetic nanocarriers has shown beneficial effects, including enhanced lipid membrane interactions, reduced toxicity, augmented receptor-mediated (gp60, gp30, gp18 and SPARC receptors) uptake in tumour cells, and prolonged blood circulation." (PMID 38366223, 2024). "[225Ac]Ac-macropa conjugated compounds with one or two albumin- and PSMA-targeting moieties (mcp-M-alb-PSMA and mcp-d-alb-PSMA) prolonged the blood circulation time, specifically and highly accumulated in the tumor, and inhibited tumor growth with DNA double-strand break formation." (PMID 38564087, 2024). "However, compared with research on other types of nanocarriers, the anti-tumor research on phenolic compounds based on albumin NPs is lacking." (PMID 39070787, 2024). "Since albumin is a highly abundantprotein in the blood, the ability of the complexes to interact withBSA implies that, once in the bloodstream, the complexes may bindto HSA (human serum albumin) and be delivered to tumor cells." (PMID 38518246, 2024). "Furthermore, changes in ALB and FIB levels may signal inflammation and coagulation mechanisms involved in tumor aggressiveness and metastasis." (PMID 38824215, 2024). "A novel albumin nanoplatform containing MnO2 efficiently delivers PDT, including PS IR780, as well as NLG919 and paclitaxel dimer, providing a simultaneous solution to the problems of tumor hypoxia, enhancement of ICD induction, and modulation of immunosuppressive TME." (PMID 39057071, 2024). "In addition to tumour burden, liver function indicators such as the Child‐Pugh grade, albumin‐bilirubin (ALBI) grade and albumin‐to‐alkaline phosphatase ratio (AAPR) have been reported to evaluate postoperative complications and prognosis in patients undergoing liver resection." (PMID 38961673, 2024). "The compound with the best tumor-to-kidney ratio exhibited a tumor uptake of ~24 %IA/g and a kidney uptake of ~63 %IA/g 4 h after injection, whereas the reference compound without the albumin binder had a tumor uptake of ~9 %IA/g and kidney uptake of ~161 %IA/g." (PMID 38399470, 2024).
tumor (continued). "Furthermore, retention in the tumor improved considerably (~11 %IA/g for folate with albumin binder vs. ~3 %IA/g for folate without albumin binder at 72 h after injection)." (PMID 38399470, 2024). "In addition, cyanine dyes without a meso-Cl group, as used in C19, do not remain in tumor tissues for a long period because they are unable to form covalent adducts with free thiol-containing biomolecules, like albumin." (PMID 39518106, 2024). "Since the dissociation constants of radiotracers against albumin in the low micromolar range are higher than those against targeted receptors in the nanomolar range, increased accumulation in tumors can be achieved by conjugating ABM to conventional radiotracers containing a tumor-targeting moiety." (PMID 38564087, 2024). "Furthermore, HCC patients displayed a more compromised liver function in comparison to those without tumor, showing low representation of Child-Turcotte-Pugh class A, lower platelet count, lower albumin values, and higher total bilirubin (all p < 0.001)." (PMID 36671786, 2023). "These albumin binders could be used to fine-tune the blood residence time of pyridine-based FAP-targeted radioligands to maximize tumor uptake without inducing significant hematological toxicity." (PMID 36986548, 2023). "Thus, the PNI, which is the additive value of the albumin level and lymphocyte count, might predict the response to ICI, since the PNI may reflect the local microenvironment relevant for anti‐tumor immunity and the nutritional change of the host." (PMID 37211905, 2023). "Combining the advantage of mannose and albumin, a dual-targeting mannosylated albumin nanoparticle was constructed; this nanoparticle targeting SPARC and MR (mannose receptor) can effectively target both cancer cells and M2 macrophages, leading to the reprogramming of the tumor microenvironment." (PMID 38258072, 2023). "Although the patient remained disease-free for 11 months, eventually the tumor progressed and did not respond to three lines of combined therapy (etoposide plus carboplatin with local radiotherapy, albumin-bound paclitaxel plus durvalumab, and irinotecan plus nedaplatin)." (PMID 37381647, 2023). "Furthermore, lower OS was also associated with a PS ≥ 2 (HR 2.42, p = 0.019), absence of primary tumor resection (HR 2.21, p = 0.0008), decreased albumin level (HR 1.98, p = 0.001), and elevated LDH (HR 2.07, p = 0.002) and CRP (HR 2.39, p < 0.0001) levels." (PMID 37400504, 2023). "In the Cox regression model including the landmark response at 3 months, identified positive predictive factors for OS were complete or partial response and ALBI score grade 1, whereas baseline albumin of < 30 g/L and a high sum of total tumour diameters were negative predictive factors for OS." (PMID 36764953, 2023). "Thus, unlike solvent-based paclitaxel, nab-paclitaxel exploits albumin to carry paclitaxel directly into cancer cells through a receptor-utilized carrier system, enhancing paclitaxel distribution at the tumor site." (PMID 37509639, 2023). "However, the co-localization of fetal-like FOLR2+ TAMs with Tregs and fetal-like ECs adjoining ALB+ tumor epithelial cells in HCC suggests that they do not orchestrate an immunosuppressive TME alone." (PMID 36938978, 2023). "Thus, we analyzed the biodistribution and nonspecific tumor accumulation based on the EPR effect of 89Zr-labeled human serum albumin by PET and MRI in the xenograft CAM model." (PMID 36831469, 2023). "Researchers had also constructed pH-sensitive albumin-based hydrogels using BSA, ß-propranolol was rapidly released at pH 1.0 and complete release of ß-propranolol was observed after 1 h at pH 6.8 using ß-propranolol as a model drug, and it can precisely deliver model drugs to tumor cells." (PMID 37113668, 2023).
tumor (continued). "Enhancing the blood circulation of radiopharmaceuticals by modifying small molecules with an entity that interacts with serum albumin in a non-covalent manner was identified as an effective means to increase tumor uptake and, thus, deliver a sufficient radiation dose to achieve a treatment response." (PMID 37686538, 2023). "In a second step, these albumin binder/linker constructs were conjugated to 6R-5-MTHF- and 6S-5-MTHF-based DOTA–folate conjugates to allow for the preparation of 177Lu-6R-RedFols and 177Lu-6S-RedFols and subsequent testing of their in vitro properties and distribution profiles in tumor-bearing mice." (PMID 37686538, 2023). "Various intrinsic factors affecting pharmacokinetics (PK) have been assessed in adults, including race, tumor type, age, creatinine clearance (37.1 to 272.2 mL/min), mild hepatic impairment, ECOG performance status, antidrug antibody (ADA), body weight, sex, and baseline albumin." (PMID 37828033, 2023). "In vivo, albumin nanoparticles are recognized by albumin receptor gp60; nab-paclitaxel then penetrates vascular endothelial cells by vesicular transport, enters tumor tissue, and binds to secreted acidic and cysteine-rich protein (SPARC), eventually being retained in tumor cells." (PMID 35719979, 2022). "We found that PIV was positively correlated with tumor size (r = 0.300, p < 0.05), carcinoembryonic antigen (CEA) (r = 0.214, p < 0.05) and carbohydrate antigen 125 (CA-125) (r = 0.249, p < 0.05), but negatively correlated with albumin (Alb) (r = −0.242, p < 0.05)." (PMID 36034356, 2022). "In vivo imaging studies demonstrated that Fv-LDP-D3 could selectively accumulate at tumor sites in the KYSE520 xenograft model where it was retained for a long period of time, suggesting that the properties of human serum albumin may prolong the half-life of drugs." (PMID 35416106, 2022). "Additionally, most available studies on the prognostic role of albumin levels in ICI-treated patients have limited or absent data regarding previously established ICI-efficacy biomarkers like PD-L1 and tumor mutational burden levels." (PMID 36533070, 2022). "In this way, folic acid-decorated albumin nanoparticles entrapping a natural cytotoxic agent were efficiently internalized by folate receptors overexpressing TNBC (MDA-MB-231) cells and showed a significantly higher antiproliferative activity in these tumor cells." (PMID 35267507, 2022). "An albumin-based AIE nanoprobe, B-TT AIE dots could induce endocytosis mediated by the gp60 receptor on orthotopic glioma and achieve in vivo NIR-II imaging and image-guided tumor surgery in mouse models." (PMID 35781601, 2022). "Despite of studies on tumor-related antigens, inflammation has been reported to assist in cancer initiation and progression for years, and the prognostic significance of systemic inflammatory immunity markers, such as NLR, PLR, MLR, fibrinogen, D-dimer and albumin has been of paramount interest." (PMID 35448194, 2022). "Some authors have shown that the tumor length, the number of tumors, treatment before tumor rupture, alanine aminotransferase level, bicarbonate level, age, antitumor treatment during follow-up, and albumin level are prognostic factors for tumor rupture regardless of surgery." (PMID 35493302, 2022). "The Okuda staging system was the first classification system to combine tumor sizes, measures of liver function, bilirubin levels, serum albumin, and tumor size with patients classified as either stage I (not advanced), stage II (moderately advanced), or stage III (very advanced)." (PMID 35573558, 2022). "They found that IR-780 generated a higher fluorescent signal in the serum compared to ICG (that does not bind to albumin), and they speculate that IR-780-albumin adducts increase the half-life and the tumor uptake capacity of carbocyanines." (PMID 34395247, 2021).
tumor (continued). "Bovine serum albumin is extensively used as a material for drug delivery, showing several advantages, such as biodegradability, non-toxicity, and non-immunogenicity, as well as a dual targeting ability to tumour tissues." (PMID 35052723, 2021). "However, tumor length, serum albumin, pTNM stage, and multiple primary malignancies were not independent risk factors." (PMID 34868958, 2021). "Additionally, evaluation of serum AFP level and albumin-bilirubin (ALBI) grade, along with liver cirrhosis, tumor margin, and radiomics signatures have increased ML-based contrast-enhanced CT performance accuracy in the prediction of HCC recurrence rate after curative tumor resection." (PMID 33562077, 2021). "The large variation in the degree of tumor microenvironment infiltration in the CRLMs was further illustrated by the gene expression levels of the hepatocyte differentiation marker ALB, which was highest in the non-malignant liver samples and decreased gradually in the CRLMs along PC1." (PMID 34470666, 2021). "This viscosity could make the albumin–ALG conjugates a suitable carrier for cells or drug delivery, and it was recently revealed that alginate-containing particle elasticity directs tumor accumulation, suggesting that it can design a parameter to enhance tumor delivery efficiency as well." (PMID 34206983, 2021). "However, DOX fluorescence of Al-ProD in tumor tissues was significantly stronger than free DOX at all time points and was retained for 72 h of injection, which indicates high tumor accumulation by albumin-mediated passive targeting effect." (PMID 35056979, 2021). "Poised with unique advantages in drug transportation, RBC-based systems were further developed and in yet another study, an albumin bound NIR dye and DOX as a chemotherapeutic agent were co-encapsulated inside the RBCs and their surfaces were modified using target protein to achieve tumor targeting." (PMID 33802156, 2021). "A combination of three parameters in routine clinical practice, including the presence or absence of PVT and tumor multifocality plus blood albumin levels, was used as a tool that identified distinct subsets of patients with large-sized HCC with typical clinical characteristics and survival." (PMID 33546234, 2021). "Tumor tissues stained with H&E and TUNEL also showed greatly elevated damaged areas and apoptosis in the Al-ProD group compared with the free DOX and saline groups, which clearly indicated the potent antitumor efficacy by albumin-mediated passive targeting of Al-ProD." (PMID 35056979, 2021). "In univariate analysis, OS was significantly related to tumor size (P = 0.026), Enneking stage (P < 0.001), pathological fractures (P = 0.039), local recurrence (P = 0.033), metastasis (P < 0.001), NLR (P < 0.001), LMR (P = 0.004), albumin (P = 0.037), and NPS (P < 0.001)." (PMID 32000789, 2020). "Thus, we considered that in the subgroup of patients with preserved liver function, which means that the ability of synthesis of albumin is relatively preserved, PNI would more accurately reflect pro-tumor inflammatory and nutritional status than in those with impaired liver function." (PMID 33129309, 2020). "By multicolor fluorescence immunostaining, we confirmed that the murine tumor cells within intermediate area shared similar intermediate phenotype with cultured hepatoblasts which simultaneously express biliary marker (e.g., CK19), hepatocellular marker (e.g. ALB)." (PMID 32190288, 2020). "However, this correlation was not linear in subsets of patients with tumor number >3, ALB ≤35 g/L, or TBIL >21 μmol/L." (PMID 33505912, 2020). "However, the interactional mechanism between ALB and tumor is quite complicated and not entirely clear." (PMID 32089687, 2020).
tumor (continued). "Other factors previously identified as influencing the PK of reference bevacizumab, such as tumor burden (measured as the longest tumor diameter in the current study), baseline alkaline phosphatase, and baseline albumin, were not identified as significant covariates in our analysis." (PMID 31768697, 2020). "The combined inflammatory and nutritional model predicting OS included pN stage, tumor differentiation grade, neutrophil count, and BMI, and the equivalent model predicting DFS included pN stage, tumor differentiation grade, neutrophil count, NLR, and serum albumin." (PMID 33215031, 2020). "On multivariate analysis, factors that were independently associated with survival included age >70 years, BMI >22 kg/m2, comorbidities, preoperative albumin of 4.0 g/dL, undifferentiated histology, preoperative macroscopic type 4 tumor, and advanced Stage but not preoperative wait time." (PMID 34142081, 2020). "For several proteins, like ALB and KNG1, the discordance between low gene expression levels in CCA tumor tissue and increased peptide levels may be explained in part by increased expression of these proteins in tissue adjacent to the tumor." (PMID 31900160, 2020). "The most important clinical event associated with poor survival was the development of early ascites after DEB-TACE-1 (median OS, 17 months), which was closely related to the history of ascites, albumin and hemoglobin but not to tumour load or to response to therapy." (PMID 32487071, 2020). "To date, the clinical approvals for tumor therapy are organic materials, including liposomes (pegylated or non-pegylated) and albumin, while inorganic materials are used for tracking and molecular imaging functions, and only superparamagnetic iron oxide (SPIO) nanoparticles are approved in clinical." (PMID 33408716, 2020). "Therefore, AKI stage is an independent risk factor for overall survival of HCC patients undergoing TACE regardless of BCLC tumor stage, serum albumin level and presence of ascites." (PMID 33315944, 2020). "Thus, serum ALB and ALP might reflect tumor progression, and can, therefore, be used to predict clinical outcomes." (PMID 32517802, 2020). "This does not affect the results of urine albumin in healthy dogs, however in dogs with urinary or gastrointestinal tract diseases, inflammation or neoplasia, serum albumin could affect the result of urine albumin concentration." (PMID 33137980, 2020). "Because many malignant tumor cells express highly specific receptors such as human epidermal growth factor receptor 2 (HER2), transferrin receptor (TfR), and FA receptor (FR), albumin NPs can be chemically modified with the corresponding ligands to provide targeted tumor delivery." (PMID 31623082, 2019). "Tumor-targeted albumin NPs for the co-delivery of CBZ and indocyanine green with irradiation were studied; with this, there was an improved antiproliferative ability (83.5%), and this achieved a higher tumor inhibition rate (91.3%) and improved anti-tumor efficacy in a 4T1 tumor-bearing mice model." (PMID 30934535, 2019). "In addition, other parameters, including age (<60/≥60 years), tumor size, depth of invasion, lymph node involvement, TNM stage, adjuvant chemotherapy, and fibrinogen and pre-albumin levels, could also significantly predict OS." (PMID 31772657, 2019). "UNOS was used in this context to assess tumor burden given that albumin is not a component of UNOS." (PMID 31238514, 2019). "Nanoparticles encapsulation based on chitosan, polymer micelles, liposome, and serum albumin improved the stability and in vitro biocompatibility of RES, which is beneficial for biomedical applications in protection against ultraviolet radiation, radiological injury, β-amyloid disease, and tumor." (PMID 30564121, 2018). "Indeed, recurrent integrations are most frequently found in the promoter region of human hTERT gene, but have also been observed in MLL4, CCNE1, and ALB genes, in tumour samples but not in the matched non-tumour samples." (PMID 30037029, 2018).